PIN1 (peptidylprolyl cis/trans isomerase, NIMA-interacting 1)
Diseases named in the same sentence as PIN1 in open-access papers (continued):
Sharing a sentence is not in itself a finding about the gene and the disease.
cancer (continued). "Given the critical role of Pin1 in cancer, here we review the recent findings about dysregulation, mechanisms, and biological functions of Pin1 in cancer cells, and also discuss the significance and potential applications of Pin1 dysregulation in human cancer." (PMID 32296699, 2020). "Although many studies have been already carried out to elucidate the molecular mechanisms and different biomarkers which regulate the activity of Pin1 towards the cancer development and drug resistance, the downstream targets mediating Pin1 functions remain to be identified." (PMID 31015482, 2019). "Many studies have revealed a relationship between Pin1 and cancer." (PMID 31795496, 2019). "In this review we will describe how cellular processes normally regulated by PIN1 could impact the pathogenesis of cancer." (PMID 30873382, 2019). "Interestingly, the expression of a group of mRNAs deregulated in AD and/or cancer are targeted by Pin1, tau and PARN, further supporting overlapping functions for these factors in the nucleus." (PMID 31749682, 2019). "Moreover, we and others have already shown that knockdown or inhibition of Pin1 is related with the decrease in tumorigenesis and increase in sensitivity of cancer cells to different anticancer drugs such as Tamoxifen and Trastuzumab13,16–18." (PMID 31015482, 2019). "Of note, PIN1 crucially impacts EGFR-promoted Warburg effect in cancer cells by inciting nuclear localization of the Pyruvate Kinase 2 (PKM2), which induces c-MYC expression, resulting in turn in the upregulation of the glucose transport protein 1 (GLUT1) and lactate dehydrogenase A (LDHA)." (PMID 30873382, 2019). "Accordingly, PIN1 inhibition has been considered as an attractive strategy for cancer therapy." (PMID 30789902, 2019). "Indeed, neurodegeneration is mainly associated to low levels or activity of PIN1, while on the contrary overexpression of PIN1 is prevalently found in cancers and inflammatory diseases." (PMID 30873382, 2019). "Several miRNAs have been found to inhibit PIN1 expression in cancers." (PMID 32010690, 2019). "However, Pin1 is overexpressed and/or activated by multiple mechanisms in many common human cancers and acts on multiple signaling pathways to promote tumorigenesis." (PMID 31888570, 2019). "This is the first report clarifying the role of Pin1 in lipid metabolism in cancer cells, and may thus provide insights useful for developing new anti-cancer drugs." (PMID 30899433, 2019). "Indeed, Pin1 plays opposite roles in the pathogenesis of both diseases, being overexpressed in many cancers and inhibited in AD." (PMID 31749682, 2019). "Given that PIN1 is deregulated in many human cancers, our findings also provide insights into how the disruption of FA pathway signaling may be connected to the genome instability of PIN1-related cancers." (PMID 30789902, 2019). "Thus, Pin1-mediated inhibition of Fbw7 is a key signaling pathway that regulates the stability of various oncoproteins in cancer." (PMID 30783083, 2019). "Pin1 has even been shown to promote cancer stem cell metastasis and tumorigenesis." (PMID 31861908, 2019). "We thus investigated the role of Pin1 in lipid metabolism in cancer cells." (PMID 30899433, 2019). "Pin1 is overexpressed in many human cancers and drives numerous oncogenic processes including drug resistance, tumour development in vitro and in vivo, and poor clinical outcomes in human cancer patients." (PMID 31015482, 2019). "Therefore, the ACC1 activity per protein is apparently enhanced through suppression of AMPK activity in most cancers with increased Pin1 expression." (PMID 30899433, 2019). "Therefore, it is likely that the growth-enhancing effect of Pin1 in cancer cells is mediated at least partially by the stabilization of ACC1 protein, corresponding to the well-known potential of Pin1 inhibitors as anti-cancer drugs." (PMID 30899433, 2019). "In fact, Pin1 strongly promotes both cancer development and growth through various pathways." (PMID 31795496, 2019).
cancer (continued). "On the other hand, Pin1 reportedly contributes to the malignant features of cancer cells." (PMID 30899433, 2019). "In human cancers PIN1 is prevalently overexpressed and essential for cancer cell proliferation and induction of centrosome amplification, two early clinico-pathological hallmarks of cancer." (PMID 30873382, 2019). "The aberrant Pin1-mediated inflammation contributes to numerous diseases, including cancer." (PMID 30158600, 2018). "Hence, altered Pin1 function can play a profound role in pathogenesis of human disease, notably cancer." (PMID 29848341, 2018). "PIN1 may also have an anti-cancer role depending on the cellular context; therefore PIN1 has been called a conditional tumor suppressor gene." (PMID 30723410, 2018). "Pin1 simultaneously activates and inactivates numerous oncoproteins and tumor suppressors, respectively, as well as globally downregulates microRNAs in cancer cells by inhibiting their biogenesis." (PMID 30093655, 2018). "Through this positive feedback loop, PIN1 may contribute to the G1 checkpoint progression through phosphorylation of Rb and over-expression of PIN1 and cyclin D1 in cancers." (PMID 30534074, 2018). "Because of the lack of published papers reporting on PIN1 somatic mutations, we obtained deposited genetic data on these mutations in different tumor types from the cBioPortal for Cancer Genomics and COSMIC (Catalog of Somatic Mutations in Cancer)." (PMID 30723410, 2018). "Indeed, PIN1 over-expression has been found in many cancers and it promotes uncontrolled cell proliferation and malignant cell transformation in different cancer models." (PMID 30534074, 2018). "Therefore, the function of the TGF-β pathway is complex and Pin1-mediated TGF-β pathway in cancer requires a deeper investigation." (PMID 30158600, 2018). "Abundant evidence illuminated that Pin1 is involved in cancer-induced angiogenesis." (PMID 30158600, 2018). "Thus, ATO uptake via AQP9 regulates its ability to induce Pin1 degradation and inhibit cancer cells." (PMID 30093655, 2018). "Thus, ATO and ATRA cooperately ablate Pin1 to simultaneously block multiple cancer-driving pathways." (PMID 30093655, 2018). "Hence, the mechanisms of Pin1-induced cancer progression and targeting Pin1 for cancer therapy are worthy of further investigation." (PMID 30158600, 2018). "In cancers, Pin1 promotes and suppresses numerous oncogenes and tumor suppressors, respectively." (PMID 30158600, 2018). "Thus, ATO and ATRA cooperatively ablate Pin1 to block multiple cancer-driving pathways and inhibit tumor growth in TNBC cell xenografts and PDOXs." (PMID 30093655, 2018). "Increasing evidence showed that Pin1 is a potential target for cancer therapy." (PMID 30158600, 2018). "Inhibition of Pin1 significantly reduces the cancer-induced angiogenesis." (PMID 30158600, 2018). "Thus, multiple independent analyses demonstrate that ATO and ATRA synergistically target Pin1 to inhibit its numerous cancer-related pathways." (PMID 30093655, 2018). "However, pRb is usually inactivated in cancer cells due to reduced expression and/or continuously hyperphosphorylation, which partially attribute to Pin1." (PMID 30158600, 2018). "The oncogenic functions of PIN1 make it an attractive target for cancer therapy." (PMID 30534074, 2018). "Juglone is effective to suppress multiple cancer cells and universally used in Pin1 research." (PMID 30158600, 2018). "Although ATO and ATRA each have other anticancer mechanisms, their cooperative Pin1 inhibition likely plays a major role in mediating their ability to block multiple cancer-driving pathways and eliminate TICs in TNBC, two major sources of drug resistance in current cancer therapy." (PMID 30093655, 2018).
cancer (continued). "This process is thought to lead to PIN1 overexpression in cancers in which PLK1 is overexpressed." (PMID 30314361, 2018). "In this review, we summarized the detailed mechanisms of Pin1 that contribute to these cancer capabilities and certain Pin1-targeted small-molecule compounds that exhibit anticancer activities, expecting to facilitate anticancer therapies by targeting Pin1." (PMID 30158600, 2018). "Pin1 also increases the invasion and metastasis of cancer by activating the NOTCH pathway." (PMID 30158600, 2018). "In cancer, PIN1 overexpression leads to pRb pathway iperactivation." (PMID 30723410, 2018). "Similarly, inhibition of PIN1 impairs cancer progression in a mouse model of NOTCH3-induced T-cell acute lymphoblastic leukemia." (PMID 30314361, 2018). "Indeed, the regulation of Pin1 in cancer against that in neurodegenerative diseases is inversely related." (PMID 30460195, 2018). "Pin1 has been extensively studied due to its diverse involvement in many signaling pathways that has many implications in various diseases, with great emphasis on cancer and neurodegenerative diseases." (PMID 30460195, 2018). "To assess whether KPT-6566 treatment impaired cancer cells viability by inducing both proliferation arrest and cell death, we performed a Trypan blue assay in control- or PIN1 silenced MDA-MB-231 cells treated with DMSO or KPT-6566." (PMID 28598431, 2017). "However, it was challenging to evaluate the significance of targeting Pin1 in cancer treatment until the recent identification of all-trans retinoic acid (ATRA) as a Pin1 inhibitor." (PMID 28262728, 2017). "Overexpression of PIN1 was found to enhance cancer growth and aggressiveness in NPC17." (PMID 28676695, 2017). "Since shRNA could have off-target effects and it is still very challenging to deliver shRNA to tumors for cancer therapy, we used a small molecular Pin1 inhibitor, ATRA, which has been identified through a mechanism-based screening from a compound library." (PMID 28404959, 2017). "Taking into consideration the emerging role of Pin1 as a critical factor in neurodegenerative diseases and cancer, our findings provide novel clues that may be helpful to understand the underlying mechanisms and to develop novel disease models." (PMID 28426725, 2017). "However, the correlation between Pin1 overexpression and cancer progression suggests that stringent control of Pin1 levels is important for normal physiology." (PMID 28426725, 2017). "Notably, Pin1 promotes cancer development by turning on and off dozens of oncogenes and tumor suppressors, respectively." (PMID 28404959, 2017). "Thus, miR-140-5p exerts potent anticancer activity against HCC by ablating Pin1 and thereby blocking multiple cancer pathways simultaneously." (PMID 28383568, 2017). "Finally, chemical or genetic Pin1 ablation blocked multiple cancer-driving pathways simultaneously in HCC cells." (PMID 28262728, 2017). "Importantly, such miR-140-5p overexpression also inhibited multiple Pin1-dependent cancer pathways and suppressed tumor growth of human HCC cells in mice." (PMID 28383568, 2017). "Accumulating evidences have demonstrated that Pin1 plays a key role in cancer development, progression and prognosis by turning on more than 40 oncogenes/growth-promoting proteins and turning off more than 20 tumor suppressors/growth-inhibiting proteins at the same time." (PMID 28404959, 2017). "PIN1 is a promising therapeutic target for cancer treatment." (PMID 28598431, 2017). "Furthermore, like Pin1 knockdown, miR-140-5p exerted potent anticancer activity against HCC by targeting Pin1 to block multiple Pin1-dependent cancer pathways simultaneously, thereby suppressing the migratory, invasive and proliferous capacity of HCC cells." (PMID 28383568, 2017). "A complex picture was also depicted on the role of Pin1 in cancer." (PMID 28426725, 2017).
cancer (continued). "Moreover, miR-140-5p inhibits multiple Pin1-dependent cancer pathways and suppresses tumor growth in mice." (PMID 28383568, 2017). "Thus, inhibition of Pin1 by chemical inhibitors or genetic knockdown has a unique property to inhibit multiple cancer-driving pathways at the same time in the complex cancer type HCC." (PMID 28262728, 2017). "Thus, Pin1 represents a novel promising therapeutic target for treating highly heterogeneous cancer HCC." (PMID 28262728, 2017). "Thus, targeting Pin1 offers a promising therapeutic approach to simultaneously stop multiple cancer-driving pathways in HCC." (PMID 28262728, 2017). "Normal cells express lower levels of PIN1 than cancer cells." (PMID 28598431, 2017). "Moreover, chemical or genetic ablation of Pin1 blocked multiple cancer-driving pathways simultaneously." (PMID 28262728, 2017). "We and others have shown that Pin1 regulates multiple cancer pathways." (PMID 28383568, 2017). "Given the obvious effects of ATRA on Pin1 protein levels, multiple cancer-driving pathways and cell growth in HCC in vitro, a critical question is whether ATRA suppresses HCC tumor growth in vivo." (PMID 28262728, 2017). "Notwithstanding, potent PIN1 inhibitors are still missing from the arsenal of anti-cancer drugs." (PMID 28598431, 2017). "Our results suggest that the down-regulation of miR-140-5p might also promote tumor growth and metastasis of many other cancers by directly increasing Pin1 expression to activate multiple cancer-driving pathways." (PMID 28383568, 2017). "The unique prolyl isomerase Pin1 regulates numerous cancer-driving pathways." (PMID 28404959, 2017). "Moreover, upon KPT-6566 treatment, same effects were observed on endogenous PIN1 in cancer cell lines of different origins, and on HA-tagged PIN1 protein ectopically expressed in PIN1 knockout MDA-MB-231 cells." (PMID 28598431, 2017). "Interestingly, although Pin1 is important for cancer cells growth, it is dispensable for normal cell growth." (PMID 28262728, 2017). "Thus, ATRA simultaneously blocks multiple Pin1-regulated cancer-driving pathways, an attractive property for treating aggressive and drug-resistant tumors." (PMID 27244887, 2017). "As a result, Pin1 serves as an important mediator in regulating physiological processes and pathological conditions, such as the cell cycle, cell proliferation, cell apoptosis, Alzheimer’s disease and cancer." (PMID 27658202, 2016). "In this article, we also consider its inactivation constituting a promising therapeutic strategy for cancer patients, and we believed that targeting Pin1 pathway could represent a novel modality for treating PTC patients." (PMID 27029791, 2016). "Furthermore, it is likely that further studies will be necessary to validate the clinical application of inhibitors of PIN1 in the management of cancer." (PMID 26784107, 2016). "Thanks to Pin1’s complicated networks with so many pathways in plenty of cancer cells, drug companies such as Pfizer Global R&D and Vernalis Ltd as well as several academic laboratories have developed some anti-cancer therapy targeting Pin1." (PMID 27029791, 2016). "All those outcomes indicated that the Pin1 gene plays an oncogenic role in tumorigenesis, and we could make use of it for cancer treatment." (PMID 27029791, 2016). "Thus, down-regulation of Pin1 in tumors leads to a strong impairment in cancer cell dissemination and maintenance." (PMID 26943576, 2016). "Together this study suggests that Pin1 overexpression and subsequent sustaining of Rb hyperphosphorylation may have an important pathological role in cancer development." (PMID 25675300, 2015). "In HCC, Pin1 can form a complex with hepatitis B virus x protein (HBx), a well-known hepatocarcinogenetic factor, and overexpress in cancer tissues, indicating that Pin1 may promote hepatocarcinogenesis." (PMID 25623232, 2015).
cancer (continued). "Hence, this study suggests a novel molecular mechanism in which the Pin1-mediated modulation of Rb phosphorylation has an important role in cancer development." (PMID 25675300, 2015). "This is likely the case in cancer where Pin1 is often overexpressed." (PMID 25874604, 2015). "By contrast, the inhibition of PIN1 in cancer cells may trigger apoptosis or suppress the transformed phenotype." (PMID 25120724, 2014). "It is also possible that some polymorphisms in the amyloid pathway may be inversely associated with cancer and AD; peptidylprolyl cis/trans isomerase, NIMA-interacting 1 (PIN1) has been proposed as one such candidate." (PMID 25400589, 2014). "Taken together, the data underscore the role of Pin1 in regulating the stability of several eukaryotic mRNAs, lending further support to the view that Pin1 inhibitors could be important for anti-cancer therapy." (PMID 24416409, 2014). "The increased Pin1 expression may contribute to advanced cancer stage and inferior survival duration." (PMID 25160749, 2014). "Finally, Pin1 is essential for IR-induced cell death in zebrafish embryos and in human cancer cells, highlighting a fundamental role in the DNA damage-triggered apoptotic response." (PMID 24982848, 2014). "The findings that Pin1 is downregulated in degenerating neurons from AD patients but its expression and activity is elevated in many cancers including those of the breast, prostate, brain, lung, and colon, provides support for the argument that Pin1 can serve as a molecular switch." (PMID 25071582, 2014). "In this study, we aimed to elucidate biological activities of Pin1 in ESCC cancer cells." (PMID 25160749, 2014). "However, the specific target or client of Pin1 in cancer cells and the client's importance in cancer remain to be explored." (PMID 25398907, 2014). "The overexpression of PIN1 is a prevalent and specific event in human cancers." (PMID 25120724, 2014). "In addition, Pin1 expression was significantly correlated with primary tumor stage (p = 0.035) and overall cancer stage (p = 0.047)." (PMID 25160749, 2014). "To summary, we demonstrate that the −667T>C polymorphism of the PIN1 do not contribute to cancer risk, while the −842C allele is associated with reduced cancer risk." (PMID 23976970, 2013). "Previous studies have shown that PIN1 was overexpressed in a variety of human cancers." (PMID 24013949, 2013). "Evidence suggested that the rs2233682 polymorphism, the synonymous change of PIN1, did not alter cancer risk." (PMID 23874525, 2013). "Since the invasion and metastasis of cancer depends on the migratory and invasive potential, the present study examined whether silencing PIN1 expression in CC cells was able to reduce migration and invasion." (PMID 24179535, 2013). "PIN1 is also involved in increasing tumor cell growth and colony formation through the upregulation of the expression of β-catenin and cyclin D1 in several types of cancer." (PMID 24179535, 2013). "It has been reported that Pin1 is markedly overexpressed in several types of human cancer." (PMID 23708493, 2013). "Therefore, PIN1 has been of increasing interest as a potential target in the treatment of patients with cancer." (PMID 24179535, 2013). "Results of this meta-analysis suggest that the PIN1 −842G>C polymorphism is associated with decreased cancer risk, but that the −667T>C polymorphism is not." (PMID 23976970, 2013). "Pin1 is overexpressed in many cancer lines, and plays an important role in oncogenesis." (PMID 23028504, 2012).